SNORA71C (small nucleolar RNA, H/ACA box 71C)
Synonyms: U71c
Gene: Small nucleolar RNA gene on chromosome 20 (38,429,670 to 38,429,803, reverse strand). Ensembl gene ENSG00000201512.
Gene Ontology:
Biological process: RNA processing
Cellular component: nucleolus
Homologues: Orthologues: chimpanzee SNORA71 (99% identical), macaque SNORA71 (93% identical), guinea pig SNORA71 (74% identical), dog SNORA71C (69% identical). Paralogues in human: SNORA71D (87% identical), SNORA71A (84% identical), SNORA60 (81% identical), SNORA71E (78% identical), SNORA71 (75% identical), SNORA71 (72% identical), SNORA71 (71% identical).